MYC (MYC proto-oncogene, bHLH transcription factor)
Diseases named in the same sentence as MYC in open-access papers (continued):
Sharing a sentence is not in itself a finding about the gene and the disease.
tumor (continued). "MYC has been deemed both a positive and negative regulator of YWHAB and FN1, hence depending on tissue and tumor type, the regulation of MYC varies." (PMID 37128318, 2023). "Several studies display that BPTF exerts positive impacts on tumor through the MYC pathway, which is a promising signal for further monitoring." (PMID 37794386, 2023). "Although MYC is an essential modulator of tumor growth via both tumor–cell intrinsic mechanisms and its influence on the tumor microenvironment, and immune effectors, direct targeting of MYC is not feasible." (PMID 36977461, 2023). "Our findings in respect to the variation of HR status and genes such as CCNE1 and MYC give a clear signal that a single biopsy to individualize treatment has the potential to significantly under-represent a patient’s unique tumor biology." (PMID 37220750, 2023). "Comprising C-MYC, MYCN, and MYCL, the MYC oncogene family has been implicated in the development of numerous tumor types." (PMID 37669923, 2023). "Amplification of the MYC gene and loss of the PTEN tumor suppressor is common in human TNBC, and the majority of PTEN loss TNBC have a copy number gain in MYC, which is prognostic for poor overall survival." (PMID 37704631, 2023). "The TNM plots revealed a high expression of c-Met/GSK3β/MYC/CCND1 in tumor tissues compared to normal colon tissues." (PMID 36672275, 2023). "Of these, control of translation appears to exert the most important effect in FLC and is targetable with the clinical eukaryotic Initiation Factor 4A (eIF4A) inhibitor zotatifin, leading to reduced c-MYC protein expression and tumor cell viability." (PMID 36692000, 2023). "A few months later, the LB showed a dramatic increase in MYC amplification and MRI confirmed massive tumor progression, while the patient’s clinical condition deteriorated." (PMID 37173990, 2023). "When nuclear staining of any intensity in ≥10% of tumor cells showed immunoreactivity with any one or more of c‐MYC, n‐MYC, or l‐MYC, the specimens were defined as MYC family‐positive." (PMID 36694106, 2023). "During the development of CRC, BET protein accumulates and binds at super-enhancers of c-MYC, thereby activating the transcription of c-MYC gene in a tumor type-specific and lineage-dependent manner." (PMID 37025163, 2023). "Worthy, LDH-A was the first metabolic target demonstrated to be directly regulated by an oncogene (MYC), and genetic or pharmacologic inhibition of LDH-A diminishes MYC-dependent tumours." (PMID 36900005, 2023). "Numerous studies have demonstrated a connection between MYC dysregulation and disruption of important biological processes, including cell cycle, tumor immune response, metabolism, cell competition, cell stemness, and a variety of other cellular activities." (PMID 37624511, 2023). "Some of the activated MYC targets exhibit cell-transforming activity, whereas some of the downregulated genes have tumor-suppressive properties." (PMID 36969025, 2023). "- miR-766-5p decreases the MYC expression level in cancer cells.- Forced expression of miR-766-5p lead to inhibition of tumor growth by targeting CBP and BRD4." (PMID 37205191, 2023). "Under hypoxic stress, activated HIF1α enhances the expression of SHMT2 in an MYC-dependent manner, which supports tumor growth by producing NADPH to counterbalance redox stress." (PMID 36755301, 2023). "Serum interleukin 6 (IL-6) decreased the expression of PTPRO by activating signal transducer and activator of transcription 3 (STAT3)/c-MYC/miR-25-3p axis, leading to PD-L1-induced immunosuppression to promote tumor growth." (PMID 38155974, 2023). "As well, C34 administration significantly increases the survival rate in a Vκ*MYC mouse model of MM, indicating that specific targeting of tumor microenvironment can compromise the development of this neoplasia." (PMID 36768145, 2023). "EZB-like-MYC+ subtype was characterized by an immunosuppressive tumor microenvironment, while EZB-like-MYC- subtype by NOTCH activation." (PMID 37032379, 2023).
tumor (continued). "And MUC1-C inhibition contributed to an inhibition of MYC gene expression, tumor cell survival and tumor growth in KRAS mutant NSCLC cells." (PMID 36895477, 2023). "Since then, MYC has become a hot gene in the field of tumor research, and even now, research on this oncogene is still ongoing." (PMID 36966168, 2023). "Flow cytometry analysis of splenocytes from sick λ-MYC Tom+/ki mice revealed tumor heterogeneity, with one group of animals harboring tumors dominated by Ig- B cells (Ig- tumors), whereas others had tumors containing mostly Ig+ cells (Ig+ tumors)." (PMID 37809061, 2023). "Our results point to MYC as a key regulator of the tumor and immune progression in genetically heterogeneous MM, which conditions clinical responses to immunotherapy." (PMID 36928817, 2023). "Dephosphorylation by the tumor-suppressive PP2A then finally targets MYC for proteasomal degradation." (PMID 36969025, 2023). "Here, the authors identify SCARB2 as a driver of tumour-initiating cells via enhanced MYC activity and evaluate the efficacy of targeting this interaction using an FDA approved drug, Polymyxin-B, in preclinical models of HCC." (PMID 37739936, 2023). "While these properties earned MYC the epithet of principal orchestrator of tumor growth, they also render MYC addiction in various cancers." (PMID 37400551, 2023). "This compound blocks MYC-driven transcription and MYC-dependent tumor cell growth in a nanomolar range and binds with high affinity to the bHLH-LZ domain of MYC." (PMID 36969025, 2023). "Because CCAT1 expression is linked to c-MYC upregulation, and c-MYC deregulation has a significant impact on cancer proliferation and migration, it can be classified as a tumor oncogene." (PMID 36624401, 2023). "Further, RNA-seq transcriptome analyses showed that AR-V7 potentiated several cancerous c-MYC downstream genes and suppressed a tumor suppressor Claudin 7 (Cldn7) that was upregulated by c-MYC overexpression." (PMID 36746917, 2023). "In the same study, analysis of circulating tumor DNA (ctDNA) revealed the progressive onset of MYC, EGFR, FGFR2, and MET amplifications in the progression phase of the disease." (PMID 35834132, 2023). "Inhibition of integrin CD11b can induce MYC expression, thereby promoting bone marrow cell polarization and tumor growth." (PMID 36966168, 2023). "In lung adenocarcinoma, significantly low expression of METTL3 inhibits m6A modification and translation of the E3 ubiquitin ligase FBXW7, resulting in reduced levels of ubiquitination and degradation of oncogenes such as MYC, accelerating tumor metastasis." (PMID 37996892, 2023). "Conversely, removal of Dox chow from mice with initially resistant disease resulted in tumor regression, suggesting that reducing c-MYC expression sensitizes tumors to T/CQ treatment." (PMID 36719686, 2023). "MYC inactivation has been studied as a therapeutic target, as its inactivation induces tumor cells to undergo terminal differentiation into mature bone cells." (PMID 37894411, 2023). "These E3 ubiquitin ligases act as tumor suppressor genes and are downregulated in tumors to stabilize MYC protein expression and promote tumor development." (PMID 38093312, 2023). "In recent years, research showed the great significance of the MYC oncogene to the differentiation and proliferation of many tumor cells and glycolysis metabolism." (PMID 36814917, 2023). "MYC-amplified tumor cells are highly sensitive towards treatment with ATP-competitive PLK1i as a monotherapy." (PMID 37183219, 2023). "Unexpectedly, we found that pre-tumor stage λ-MYC mice showed a marked block at the Pro-B cell stage, accompanied by a pronounced reduction in the subsequent Pre-B cell subset." (PMID 37809061, 2023). "This review first briefly introduces the structure and function of MYC and its function in driving tumor immunosuppression to link MYC targets with tumor immunotherapy and introduces multiple cancer immunotherapies from different perspectives." (PMID 36966168, 2023).
tumor (continued). "Young, pre-tumor stage λ-MYC mice showed a prominent block in early B cell differentiation that resulted in the generation of highly aggressive tumors lacking surface BCR expression." (PMID 37809061, 2023). "High c-MYC protein levels not only drive tumor initiation and progression, but are also essential for tumor maintenance, making c-MYC a highly attractive target for anti-cancer therapy." (PMID 37705742, 2023). "Depending on the chemical nature, different carrier systems can be used to deliver the compound into MYC-dependent tumor cells." (PMID 36969025, 2023). "For example, the tumor suppressors, miR-22, miR-24, or let-7, are all able to disrupt MYC E-box binding through connecting to the 3′ UTR region of MYC, reducing its effect on target gene transcription." (PMID 37443779, 2023). "On the other hand, the MYC/c-MYC protein appears to induce apoptosis, which counteracts its pro-tumor effects." (PMID 37509254, 2023). "A vast majority of HCC cases include upregulation of the oncogene c-MYC, which manifests as a more advanced, aggressive, and fast-growing tumor phenotype." (PMID 37628798, 2023). "We found that MYC specifically boosts disialyl-T expression and that tumor disialyl-T engages Siglec-E in mice and Siglec-7 in humans, to inhibit macrophages and promote immune evasion in vivo." (PMID 36897988, 2023). "Further single-nucleus-RNA-sequencing revealed that TAM from LP diet-treated MYC-PyMT tumor had higher transcripts for phagolysosome biogenesis, phagocytosis, and endocytosis due to the nuclear translocation and transcriptional regulation of TFEB/TFE3." (PMID 37884533, 2023). "Dietary restriction of vitamin B5 reverses several MYC-driven metabolic changes and hampers tumor progression." (PMID 37946084, 2023). "According to MYC rearrangement, the EZB-like-MYC+ subtype was distinguished by poor prognosis and CD8+T cell deficiency within tumor microenvironment." (PMID 37032379, 2023). "Tumor cell content, immunohistochemical findings, and the contribution of MYC alterations were comparable between primary refractory cases and the comparison cohort." (PMID 36923431, 2023). "Many “star” transcription factors, such as MYC and HIF1α, govern tumor metabolic reprogramming, and expression of these master regulators can also be modulated by m6A methylation." (PMID 37192910, 2023). "Here, we found that HIF1A-As2 KD by ASO synergistically with the MYC-specific inhibitor significantly suppresses tumor growth in the PDX model." (PMID 37041291, 2023). "MYC oncoprotein deregulation is a common catastrophic event in human cancer and limiting its activity restrains tumor development and maintenance, as clearly shown via Omomyc, an MYC-interfering 90 amino acid mini-protein." (PMID 36830948, 2023). "In the 1980s, PVT1 was discovered and named as a MYC activator, and it has presented a tumor-promoting effect in a variety of malignant tumors." (PMID 36869031, 2023). "Downregulation of a MYC signature has been reported in vivo upon treatment of KRASG12C lung tumors with KRASi MRTX-849 using drug concentrations eliciting significant tumor growth inhibition." (PMID 37816716, 2023). "To further analyze the mechanisms of the tumor inhibition ability of mRNA nano-lantern, we evaluated the expression level of Smad4, downstream transcriptional regulatory genes, MYC, VEGFC, and CXCL5 in tumor tissues by Western blot." (PMID 36894556, 2023). "One study indicated that, in a variety of cancers, activated MYC in tumor cells participates in miR-29c-3p-targeted CD276 signaling to mediate immune surveillance, thereby avoiding NK-cell cytotoxicity." (PMID 36966168, 2023).
tumor (continued). "On the one hand, the downstream signaling pathway of IGF‐1R has multiple crossing sites with oncogenes such as Ras and c‐MYC, which can regulate each other to play a role in leading to tumor formation." (PMID 36994237, 2023). "MYC by itself is considered undruggable, but MYC‐driven tumours exhibit various dependencies that are essential for cancer survival and can be targeted pharmacologically." (PMID 36855776, 2023). "In preclinical animal models, MYC inactivation can result in sustained tumor regression, a phenomenon that has been attributed to oncogene addiction." (PMID 37998757, 2023). "Dysregulated c-MYC and CYCLIN D1 have shown to be associated with aberrant tumour growth in many human cancers." (PMID 37127581, 2023). "GMYC mice that were exposed to dox during the gestation period from E0-E21/P0 saw similar inactivation of MYC and a subsequent tumor-free life span in 90% of cases, suggesting that these tumors arise during embryonic development." (PMID 36869047, 2023). "MYC positively affects many regulatory processes, such as tumor cell adhesion, antiapoptosis, and tumor angiogenesis, and its expression level in tumor tissues is closely related to tumor progression and prognosis." (PMID 36994237, 2023). "For example, specific inhibition of the WDR5–MYC interaction has shown a reduction in tumor malignancy, as the function of the MYC transcription factor relies on WDR5 for gene recognition." (PMID 37568727, 2023). "It is the main nucleolar interaction partner for the p14ARF tumor suppressor and the c-MYC oncoprotein, and knockdown experiments have identified NPM1 as a promising target for cancer therapy." (PMID 36743470, 2023). "Previous studies have extrapolated an exemplary role of MYC in the metabolic reprogramming of tumor cells." (PMID 37626036, 2023). "Lack of novel therapeutics is in part due to the unique biology of SCLC, which is driven by mutations in tumor suppressors and amplifications of transcription factors like NFIB and MYC." (PMID 36690626, 2023). "This analysis showed that tumors in the DLRS-low group were significantly enriched for multiple cancer hallmark-related pathways such as MYC signaling, KRAS signaling, and epithelial mesenchymal transition that are associated with aggressive tumor phenotypes." (PMID 37557177, 2023). "To further characterize BM differentiation in pre-tumor stage λ-MYC mice, we analyzed the expression of c-MYC protein and RNA." (PMID 37809061, 2023). "When FACT was silenced, c-MYC expression was reduced, and tumor cells were prevented from re-entering the cell cycle." (PMID 36691066, 2023). "On the other hand, in KIRP, CDK1, CDK4, HIPK2 and MYC expression increased with the pathological and clinical stage of the tumor, whereas KLF4 decreased." (PMID 37047552, 2023). "This was thought to be mediated through the suppression of STAT3 signaling pathway and its downstream genes BCL2, c-MYC, and Survivin, which affect tumor growth by inducing apoptosis." (PMID 37189618, 2023). "HnRNP H1 expression was found to be anticorrelated with the MYC score across many tumor types including lung, breast, and prostate, consistent with the repression of exon 5 by MYC." (PMID 37399401, 2023). "Collectively, these results demonstrate that both C.B and C.B CM exert an antitumor effect in CRC and imply that both anti-cancer effects of C.B and C.B CM involve MYC downregulation and tumor immunity/T cell infiltration." (PMID 36941257, 2023). "Tumors in this model develop clonally at embryonal/postnatal time points and show dependence on MYC signaling as tumor cells are efficiently eradicated upon MYC inhibition." (PMID 36869047, 2023).
tumor (continued). "This MYC-MAX compound inhibits transcription of the MYC promoter, increases MYC protein levels in CAFs, and finally induces an MYC-dependent metabolic program to participate in tumor growth and development." (PMID 36966168, 2023). "Although MYC or MYCN must be involved in the tumor initiation process, we found that the MYC/MYCN pathway is suppressed in ArfARF-depleted HGG-like tumors." (PMID 36869047, 2023). "For instance, EBV activates oncogenes such as Bcl-2 and MYC and deactivates tumor suppression genes." (PMID 36826111, 2023). "Substantial evidence supports that abnormal MYC expression drives tumor onset and progression and links it to all defining features of cancer." (PMID 37711209, 2023). "Compound 8 was identified as a candidate for clinical trials due to its ability to suppress tumor growth and down-regulate MYC substantially in vivo, as well as its acceptable drug toxicity." (PMID 37142850, 2023). "Studies using mice with a regulatable Myc transgene showed that MYC-driven tumour cells die when MYC is removed." (PMID 36342579, 2023). "Collectively, BTK inhibition by tirabrutinib led to the suppression of NF-κB and ERK signaling, followed by downregulation of IRF4- and MYC-targeted genes, resulting in anti-tumor activity in TMD8." (PMID 36897912, 2023). "We noted that reducing c-MYC expression conferred sensitivity to tumors that had grown through T/CQ treatment and allowed for T/CQ-mediated tumor regression." (PMID 36719686, 2023). "MYC was the first proto-oncogene that was found to be amplified in tumor cells, and its overexpression is involved in tumor-related processes." (PMID 36966168, 2023). "Accumulating evidence has indicated that aberrations or excessive expression of MYC-mediated regulation by differential mechanisms exhibit in many types of cancer, and MYC inhibition can lead to sustained tumor suppression in some preclinical models." (PMID 37151387, 2023). "Flow cytometry analysis showed the presence of Tom+ cells in the spleen and lymph nodes of pre-tumor stage λ-MYC Tom+/ki mice and littermate controls." (PMID 37809061, 2023). "On this basis, PARPi and CDK4/6 inhibitor combinations are currently under evaluation including in MYC amplified tumours (NCT04693468)." (PMID 37430137, 2023). "We validated the newly established method on tumor tissue from tumors with MYC amplification (n = 3, pat 1, 3 & 5) and MYC gain (n = 1, pat 4)." (PMID 37173990, 2023). "Because MYC can regulate the immune response by promoting CD274 transcription in tumor cells, we investigated this possibility in the mouse models." (PMID 36928817, 2023). "Neutrophil-primed progenitor genes and MYC transcription factor regulators influence tumor progression and are prominently expressed in stem cells from CMML-1 patients." (PMID 36966168, 2023). "The fundamental of MYC biology is that MYC function differs when expressed at high levels, as in many tumor cells, versus at relatively low physiological levels." (PMID 37601651, 2023). "IHC staining and Western blotting of the tumor sections of our OS specimens also showed higher MYC protein levels than those in the tumor-adjacent normal tissue sections." (PMID 36717782, 2023). "Currently, treatment strategies targeting the biosynthesis of MYC that affect tumor cells of DLBCL have been reported." (PMID 36812125, 2023). "Among other c-MYC-regulated metabolic pathways is the polyamine metabolism pathway, which plays critical tumor-promoting roles." (PMID 36765581, 2023). "To date, the main recognized poor-prognosis genetic subtypes display tumour MYC and BCL2 translocations (‘double-hit lymphoma’) or MYC, BCL2 and BCL6 translocations (‘triple-hit lymphoma)." (PMID 37345090, 2023).